HIF1A (hypoxia inducible factor 1 subunit alpha)
Diseases named in the same sentence as HIF1A in open-access papers (continued):
Sharing a sentence is not in itself a finding about the gene and the disease.
viral infection (continued). "Taken together, innate immunity response to viral infection and its related hypoxic microenvironment is highly dependent on the expression and activity of HIF-1α." (PMID 33139969, 2020). "We performed a western blot analysis to determine the expression of HIF1α protein after virus infection in 3% O2 conditions hypoxia since physiological levels of oxygen in many tissues ranges, 3–7%." (PMID 31809522, 2019). "Activation of HIF1α protein has been observed during virus infection, leading to metabolic adaptation and allowing viral replication." (PMID 31809522, 2019). "The stabilization of hypoxia inducible factor due to viral infection activated the HIF1α dependent pathways, whereas hypoxia due to low oxygen led to activation of several other energy associated pathways such as the AMPK dependent pathways." (PMID 29746587, 2018). "NDV-induced downregulation of HIF-1α seen in the present study agrees with a number of previous reports on viral infection data." (PMID 27902314, 2016). "Alterations in calcium homeostasis, ROS production, and expression of NF-kB and HIF-1α are also expected to alter the metabolic state as was previously found for some viral infections." (PMID 20181022, 2010). "Interestingly, the elevated total HIF1α showed parallel correlation with ROS levels in mutant cells at 24 hrs after viral infection under normoxia." (PMID 40570045, 2025). "Based on the important roles of miRNAs in the virus‐host interactions, the results of this study revealed that WSSV‐miR‐N20 could suppress the virus infection by targeting HIF1a to inhibit histone lactylation process." (PMID 38874057, 2024). "To document whether viral infection could alter hypoxic conditions in mice, we examined HIF1α protein levels by immunofluorescence staining." (PMID 38670937, 2024). "To further understand the reason, we then examined whether the hydroxylase activity of EGLN1 was altered in the process of viral infection by using HIF1α hydroxylation as an indicator." (PMID 38670937, 2024). "HIF1α controls the metabolic adaptation of NK during virus infection." (PMID 36851739, 2023). "We foresee that more clinical trials evaluating the use of drugs capable of regulating the expression of HIF-1α are likely to occur in the near future due to the accumulating evidence available regarding the interplay between hypoxia and human viral infections." (PMID 34360716, 2021). "Therefore, our data revealed that SARS-CoV-2 ORF3a plays important roles in regulating HIF-1α production, proinflammatory responses, and viral infection." (PMID 34408131, 2021). "Therefore, we proposed that upon SARS-CoV-2 infection, ORF3a induces Mito-ROS production to activate HIF-1α, which in turn enhances the viral infection and aggravates inflammatory responses." (PMID 34408131, 2021). "In contrast, our findings were the polar opposite to these reports in that mice with HIF1α-deficient NK cells showed reduced control of viral infection without alteration in NK cell activation or killing ability." (PMID 34396954, 2021). "Several studies have reported an upregulation of HIF-1α during viral infections." (PMID 34360716, 2021). "HIF-1α subsequently enhanced the virus infection and pro-inflammatory responses." (PMID 34408131, 2021). "HIF1α inhibitors may be effective against viral infections that have exhibited the ability to induce HIF1 α and thrive under its activity." (PMID 32718318, 2020). "During viral infections, many studies report that HIF-1α is upregulated in infected cells, suggesting that this factor may have favorable effects for the virus, rather than for the host." (PMID 33135539, 2020). "Moreover, HIF-1α activation under normoxia is a general phenomenon in bacterial, protozoan, and viral infections." (PMID 30513781, 2018). "However, if virus infection was combined with hypoxia, the expression of HIF-1α was upregulated and nuclear translocation of HIF-1α was enhanced, thereby inducing higher levels of proinflammatory cytokines." (PMID 28536432, 2017).
viral infection (continued). "Induced HIF-1α may specifically play a role in the innate immune response to viral infection; however it is still unknown if there is a relationship with type I IFN (IFN-α or IFN-β) and type II IFN (IFN-γ)." (PMID 28484714, 2017). "Inhibition of HIF-1α translation at later times in MRV infection may occur as a result of modification of the translational machinery during virus infection." (PMID 24504474, 2014). "In summary, we demonstrate that the influence of HIV-1 proteins alone, without viral infection, is associated with pulmonary arteriopathy including accumulation of HIF-1α and PDGF as observed in the HIV-1 Tg rats." (PMID 21819559, 2011). "Furthermore, the VHL-deficient T cells displaying the constitutive activation of hypoxia-inducible factor 1-alpha (HIF1α) and enhanced constitutive glycolytic metabolism showed an equivalent ability to generate long-lived (>60 days) memory following acute viral infection." (PMID 35203357, 2022). "Moreover, hypoxia may have a considerable effect over numerous viral infections, consistent with several viruses inducing a hypoxic response upon infection to promote their replication or stabilize HIF-1α with concomitant enhanced viral gene expression." (PMID 34360716, 2021). "As our RNA-Seq data showed that the regulation of HIF by oxygen pathway and the HIF-1α signaling pathway were upregulated in the blood samples of COVD-19 patients, we speculated that HIF-1α plays an important role in regulating immune and inflammatory responses upon the viral infection." (PMID 34408131, 2021). "Finally, these types of drugs may be used against SARS-CoV-2, as ACE2 which is crucial for viral infection, decreases upon HIF-1α accumulation." (PMID 33135539, 2020). "We first determined whether MHV68 upregulates HIF1α during virus infection in culture." (PMID 31809522, 2019). "However, little is known about the role of HIF-1α during viral infections." (PMID 29222473, 2017). "HIF-1α stabilization under aerobic conditions can be linked to mitochondrial dysfunction through abnormalities in calcium homeostasis, ROS generation, NFkB signaling, accumulation of TCA cycle metabolites (succinate and fumarate), and oncogenic viral infections." (PMID 20181022, 2010). "In addition, previous studies have found activation of HIF-1α during viral infections." (PMID 18839041, 2008). "It has also been described that treatment with HIF1α-inhibitor significantly improved IFN-α/β synthesis, in turn decreasing viral infections in EGLN1c.[12C>G;380G>C] (PHD2D4E;C127S) cells in vitro." (PMID 40570045, 2025). "Differences between samples from controls and neonates with ongoing viral infection in several molecules (filaggrin, VEGF, RANTES (CCL5), HIF-1α, IL-17A and IL-1 β) were also observed, indicating an immune response associated with viral infection." (PMID 36482106, 2022). "Several studies indicated that heat shock proteins (HSP) are upregulated by viral infection, but also annexin 1 and 2, AKT serine/threonine kinase (AKT1) and hypoxia-inducible factor (HIF1a)." (PMID 32268515, 2020). "Although the role of HIF-1α in macrophages during inflammatory and antibacterial activities has been addressed in several studies, little is known about HIF-1α and viral infection." (PMID 29222473, 2017). "To determine whether HIF-1α was involved in PEDV-induced metabolic reprogramming, we examined HIF-1α expression following viral infection." (PMID 41512444, 2026). "Piezo1−/− or Piezo1 upregulation by Yoda1 treatment altered SIRT2 and HIF1α expression in neutrophils, indicating that SIRT2 and HIF1α are likely involved in Piezo1-mediated NET formation in neutrophils during the response to virus infection." (PMID 39890818, 2025).
viral infection (continued). "Secondly, investigating the mechanism of elevated ROS generation, in turn suppression of PHD2D4E;C127S and stabilization of HIF1α, and a decrease in IFN synthesis, inversely correlating with increased in viral infection in PHD2D4E;C127S monocytes as compared to PHD2WT in normoxia." (PMID 40570045, 2025). "Under normal and viral infection conditions, magnesium at a physiological concentration (0.6 mM) increased NET formation and the expression of PAD4, SIRT2 and HIF1α; upregulation of Piezo1 expression by Yoda1 treatment promoted these effects, but Piezo1−/− abolished these alterations." (PMID 39890818, 2025). "Both HIF-1α knockdown and treating the myocardial cell with QFPDD significantly reversed the increased inflammatory factors (IFN-β, IL-18, and TNF-α) mediated by viral infection." (PMID 38476329, 2024). "VSV-induced Ifn-β and Ifit1 expression was still largely lower in Irf3_P10A BMDCs than in WT BMDCs, indicating that HIF1α does not mediate the difference between WT and Irf3_P10A mice in response to viral infection." (PMID 38670937, 2024). "Since the levels of succinate affect HIF-1α activity, a key transcription factor in the expression of pro-inflammatory genes, we monitored the protein expression level of HIF-1α in the context of virus infection and mannose treatment." (PMID 38459021, 2024). "Many pieces of literature have demonstrated that after virus infection of host cells, it can regulate cellular glycolysis, fatty acid metabolism, and glutamine catabolism/glutaminolysis, the PI3K/Akt/mTOR pathway, c-myc, HIF-1α, and tumor formation." (PMID 36851737, 2023). "Mechanistically, it could be possible that a hyperglycemic state might favor virus infection as it has been shown that elevated glucose levels enhanced SARS-CoV-2 replication and cytokine expression in monocytes through stabilization of HIF-1α." (PMID 36009573, 2022). "Here, we undertook a stepwise analysis of this pathway to investigate whether virus infection alters the stability of HIF-1α and HIF-2α, since the latter isoform was also down-regulated upon virus infection, but to a lesser extent." (PMID 32244697, 2020). "However, during viral infection, e.g., COVID-19, the viral replication in lung epithelial cells can impair alveolar O2/CO2 exchange, leading to systemic hypoxia, including the CNS, which can activate aerobic glycolysis and stabilize HIF-1α in microglia." (PMID 36851739, 2023). "Instead, we show a previously unknown role for HIF1α in NK cells during MCMV infection, supporting survival rather than proliferation through efficient glucose metabolism that is required for an optimal host response to virus infection." (PMID 34396954, 2021). "Furthermore, during viral infections, such as those produced by the hepatitis C virus (HCV), HK II is overexpressed and in cells infected with the human respiratory syncytial virus (hRSV) HIF-1α suppression induced a decrease in HK II protein levels." (PMID 34360716, 2021). "In addition, treating zebrafish with the HIF1α-specific inhibitor PX478 enhances the antiviral ability against SVCV infection, suggesting that PX478 treatment may be a potential and useful strategy to protect fish against viral infection." (PMID 39601573, 2025). "However, we could not exclude the possibility that HIF-1α also plays a role in viral infection." (PMID 38476329, 2024). "HIF-1α and c-Myc control HBD1 expression in epithelial cells in a non-inflammatory manner, supporting our findings that HBD1 transcription is not altered during acute viral infection in these cells." (PMID 28253319, 2017).
anemia (60 papers, 2010 to 2026). A reduction in the number of red blood cells, the amount of hemoglobin, and/or the volume of packed red blood cells. "Hypoxia caused by anemia activates hypoxia-inducible factor (HIF)-1α, a transcription factor that upregulates pro-angiogenic and pro-inflammatory genes." (PMID 40486649, 2025). "As anticipated, pregnant rats with iron-deficient anemia exhibited a noteworthy rise in HIF-1α levels when compared to the control group." (PMID 37763272, 2023). "Previous studies have indicated an association between anemia-induced hypoxia and glomerular disease through the HIF-1α signaling pathway." (PMID 33478025, 2021). "The HIF-1α has been reportedly associated with anemia, as well as with renal interstitial fibrosis and glomerulosclerosis." (PMID 32884936, 2020). "Considering the closely association of HIF with anemia, immunofluorescence staining were performed to investigate the correlation of PD-L1 with anemia (represented as HIF-1α activity) using 30 recurrent tumors." (PMID 28881642, 2017). "Mechanistically, inflammation causes severe anemia and hypoxia in the bone environment, yet down-regulates the HIF-1α pathway in chondrocytes, thereby promoting the demise of these cells." (PMID 28687790, 2017). "It did not, however, mediate the association between tumor Nampt/PBEF/visfatin and anemia, although systemic hypoxia with subsequent upregulation of HIF1α would be the simplest explanation for an increase in Nampt/PBEF/visfatin." (PMID 26075243, 2015). "Thus, PHD-2 inhibitors designed as HIF-1α stabilizers achieved clinical efficacy in the treatment of anemia and ischemic and have been linked to cancer treatment-associated diseases." (PMID 40032892, 2025). "In comparison, loss of intestinal Hif1α didn't affect the degree of 5‐FU‐induced anemia." (PMID 38243847, 2024). "This association could be explained by anemia-induced dimerization of hypoxia-inducible factor 1 alfa (HIF-1α)." (PMID 34200349, 2021). "The lack of coordinated changes in iron-regulated genes and unaltered iron level in isolated cardiomyocytes suggest that the induction of HIF-1α in this mouse model is more likely to be related to impaired oxygen supply due to anemia than to cardiac iron deficiency." (PMID 33553263, 2020). "Also, hepcidin repression during deficiency-induced anemia is associated with an induction of HIF-1α stabilization, further triggering anemia of chronic disease, which is also seen in cancer patients." (PMID 31083487, 2019). "However, colorectal expression of Nampt/PBEF/visfatin was strongly associated with HIF1α and HIF1α corresponded with anemia in normal tissue as well (p = 0.017)." (PMID 26075243, 2015). "The small upregulation of Hif1a during iron deficiency anemia (P15 ID) was likely driven by cellular hypoxia, whereas its upregulation in the F2 IS could be driven by BDNF/TrkB signaling." (PMID 24303168, 2013). "Both the functional iron deficiency and induced anemia could upregulate Hif1α expression as well." (PMID 34675764, 2021). "A critical factor contributing to the increase in intracellular Ca2+ during anemia or hypoxia is the activation of the HIF-1α pathway." (PMID 40362253, 2025). "HIF-1α, which regulates hypoxic responses and angiogenesis, is inhibited by agents like acriflavine or stabilized in anemia therapies by HIF-PHD inhibitor roxadustat." (PMID 40650173, 2025). "Hif1α is a key regulator of hypoxia-induced transcription that coordinates metabolic and iron-uptake programs to tissue hypoxia during anemia." (PMID 41471763, 2025). "Several chemotherapeutic drugs have been applied to modulate the HIF‐1α/VEGF signaling pathway, but their hostile outcomes, like anemia and appetite loss, are alarming." (PMID 40964147, 2025). "While HIF-1α initially aids tissue adaptation by promoting angiogenesis and erythropoiesis, chronic activation in anemia can lead to pathological vascular remodeling and instability." (PMID 40486649, 2025).
anemia (continued). "Some patients were administered Roxadustat, a hypoxia-inducible factor prolyl hydroxylase inhibitor (HIF-PHI), which functions by inhibiting the degradation of HIF-1α, thereby increasing its levels and ameliorating anemia." (PMID 39717345, 2024). "PHDi that stabilize HIF-1α expression and activate the hypoxia response pathway have been developed in the last decade for treating anemia, and several of these molecules are now in clinic." (PMID 39078527, 2024). "The PHD inhibitor vadadustat, which is an α-ketoglutarate mimetic akin to DMOG, was developed to treat anemia and conditions with HIF-1α dysregulation." (PMID 37417946, 2023). "Justification for use of PHD inhibitors to treat infection has been largely based on their ability to improve insufficient or dysregulated HIF-1α–mediated metabolic adaptations to hypoxia and anemia." (PMID 37417946, 2023). "Given that both LRG1 and iron deficiency regulate HIF-1α expression, it is vital to explore the association between LRG1 and anemia." (PMID 37513518, 2023). "We also obtained liver tissues from patients with anaemia of chronic disease undergoing surgery, AMPKα1 and hydroxylated HIF1α levels were measured by immunohistochemical analysis." (PMID 35538889, 2022). "Liver tissues from adult patients with anaemia of chronic disease displayed a clear downregulation of AMPKα1 in parallel with increased levels of hydroxy‐HIF1α." (PMID 35538889, 2022). "The most advanced HIF-1α stabilizer, roxadustat (also known as FG-4592), is well investigated for the treatment of anemia by targeting HIF-1α with promising results in CKD." (PMID 35492370, 2022). "Consistently, elevated expression of hydroxy‐HIF1α in the human liver biopsy was correlated with anaemia of chronic disease." (PMID 35538889, 2022). "Currently, HIF1α inhibitors are being tested in clinical trials to treat cancers and anemia, among others." (PMID 34360716, 2021). "FG-4592 is a new HIF-PHD inhibitor that has been approved in China to treat CKD anemia by stabilizing HIF-1α." (PMID 32848792, 2020). "Hypoxia due to anemia will lead to increased HIF1α, which then activate Glucose transporter 1 and Phosphofructokinase-2 involved in glycolysis, leading to an increase of De Ritis ratio." (PMID 32451768, 2020). "The regulation of HIF-1α is a pivotal element for anemia, ischemic diseases, tissue injuries, and inflammatory diseases." (PMID 31413262, 2019). "HIF-1 mainly regulates hypoxic reaction proteins, including angiogenic factors, glycolytic enzymes and cell survival proteins, a certain degree of up-regulation of HIF-1α expression can be used to alleviate anemia in CKD." (PMID 31623681, 2019). "In fact, lots of researches have indicated the significant roles of HIF-1α, coenzyme A biosynthesis and sphingolipids biological pathways in treating anemia and related diseases." (PMID 29551975, 2018). "The specific mechanisms of anemia in NOMID mice are unclear, but this anomaly is associated with inflammation, and diminished expression of HIF-1α and its target genes, events that are associated with chondrocyte death." (PMID 28687790, 2017). "We observed that advanced rT classification and anemia status before salvage treatment was associated with high level of PD-L1 in recurrent NPC patients, and PD-L1 and was co-located with HIF-1α in recurrent tumors by immunofluorescence analysis." (PMID 28881642, 2017). "Nampt/PBEF/visfatin expression in nontumor tissue, both mRNA and protein, increased in patients with metastatic disease and mild anemia, and, on transcriptional level, correlated with HIF1α, IL1β, IL8, CCL2, and CCL4 expression." (PMID 26075243, 2015). "Conversely, pharmacological stabilizers of HIF-1α (PHD inhibitors) are in clinical development for treatment of anemia, and the potential for repositioning such drugs as “innate immune boosters” has been explored in animal models of bacterial infection." (PMID 25927232, 2015).